RNF114 (ring finger protein 114)
Description:
E3 ubiquitin-protein ligase that promotes the ubiquitination of various substrates. In turn, participates in the regulation of many biological processes including cell cycle, apoptosis, osteoclastogenesis as well as innate or adaptive immunity. Acts as a negative regulator of NF-kappa-B-dependent transcription by promoting the ubiquitination and stabilization of the NF-kappa-B inhibitor TNFAIP3. May promote the ubiquitination of TRAF6 as well. Also acts as a negative regulator of T-cell activation. Inhibits cellular dsRNA responses and interferon production by targeting MAVS component for proteasomal degradation. Ubiquitinates the CDK inhibitor CDKN1A leading to its degradationand probably also CDKN1B and CDKN1C. This activity stimulates cell cycle G1-to-S phase transition and suppresses cellular senescence. May play a role in spermatogenesis.
Synonyms: ZNF313; PSORS12
Tractability: Antibody: its Gene Ontology location is reachable by antibodies, with high confidence. PROTAC: UniProt records ubiquitination sites on it; ubiquitination databases record sites on it; its protein half-life has been measured.
Target class: Enzyme; Transferase
Gene: Protein-coding gene on chromosome 20 (49,936,336 to 49,953,892, forward strand). Ensembl gene ENSG00000124226.
Subcellular location: Cytoplasm; Nucleus
Subcellular location (Human Protein Atlas): Cytosol; Plasma membrane
Pathways (Reactome):
Immune System: Antigen processing: Ubiquitination & Proteasome degradation
Gene Ontology:
Molecular function: protein binding; ubiquitin protein ligase activity
Biological process: protein polyubiquitination; ubiquitin-dependent protein catabolic process; protein ubiquitination
Cellular component: cytoplasm; cytosol; nucleus
Genetic constraint (gnomAD): Loss-of-function variants: 3 observed, 18.01 expected, observed/expected ratio (o/e) 0.17, 90% interval 0.075 to 0.43. The upper end of that interval is the gene's LOEUF score, 0.43, which puts it in group 1 of 6, group 1 being the genes least tolerant of losing a copy. Missense variants: 215 observed, 242 expected, observed/expected ratio (o/e) 0.89, 90% interval 0.79 to 1. Synonymous variants: 97 observed, 94.39 expected, observed/expected ratio (o/e) 1.03, 90% interval 0.87 to 1.22.
Homologues: Orthologues: chimpanzee RNF114 (100% identical), macaque RNF114 (99% identical), dog RNF114 (94% identical), pig RNF114 (94% identical), rabbit RNF114 (94% identical), mouse Rnf114 (90% identical), guinea pig RNF114 (84% identical), tropical clawed frog rnf114 (50% identical), zebrafish rnf114 (48% identical). Paralogues in human: RNF166 (43% identical), RNF138 (30% identical), RNF125 (29% identical), RNF180 (21% identical).
Diseases named in the same sentence as RNF114 in open-access papers:
RNF114 is named in the same sentence as 22 diseases in open-access papers, as found by Europe PMC text mining. Sharing a sentence is not in itself a finding about the gene and the disease. The quoted sentences say what the papers report.
psoriasis (11 papers, 2012 to 2025). An autoimmune condition characterized by red, well-delineated plaques with silvery scales that are usually on the extensor surfaces and scalp. "Recent studies have identified RNF114, a gene encoding a novel ubiquitin-binding protein (E3 ubiquitin ligase), as a significant contributor to psoriasis susceptibility." (PMID 40981192, 2025). "The disease‐associated SNP, rs495337, functions as a regulatory variant that increases RNF114 expression in skin and immune cells, suggesting that overexpression of this immune‐regulatory E3 ligase contributes to psoriasis pathogenesis." (PMID 41362701, 2025). "A genome‐wide association scan for psoriasis identified a novel susceptibility locus on chromosome 20q13, pinpointing the E3 ubiquitin ligase RNF114 as the likely causal gene." (PMID 41362701, 2025). "RNF114 (also known as ZNF313) is a RING‐type E3 ligase identified as a psoriasis susceptibility gene through multiple genomic studies." (PMID 41362701, 2025). "This is consistent with genetic evidence from genome-wide association studies that implicate RNF114 as a risk locus for psoriasis, where the gene is overexpressed in lesional tissue and contributes to dysregulated immune signaling." (PMID 40981192, 2025). "RNF114 was first reported as a novel susceptibility gene for psoriasis, while several studies have demonstrated that RNF114 plays a critical role in tumor development 36,37." (PMID 35069903, 2022). "The RNF114 protein is a novel determinant of psoriasis susceptibility, and its overexpression is a crucial indicator of epithelial inflammation 9-11." (PMID 35069903, 2022). "RNF114 (RING finger protein 114, also as ZNF313, zinc finger protein 313), first identified and reported in 2003, is an ubiquitin binding protein and disease susceptibility gene for psoriasis, an immune-mediated skin disorder." (PMID 23285140, 2012). "A genome-wide association study identified rs495337, which is linked to increased expression of RNF114 in skin and immune cells, suggesting it may function as a regulatory variant influencing psoriasis risk." (PMID 40981192, 2025). "RNF114 has been previously proven to be a susceptible gene of psoriasis." (PMID 30083474, 2018). "RNF114 (E3 ubiquitin ligase RING finger protein 114) was first identified as a zinc-binding protein that promotes psoriasis development; however, its role in gastric cancer is still unclear." (PMID 35069903, 2022). "Additionally, rare promoter variants (c.-64C4A, c.-41C4T, c.-66C4A, and c.-9A4C) have been discovered to significantly reduce RNF114 expression, thereby directly affecting gene regulation in psoriasis patients." (PMID 40981192, 2025). "By enhancing NF‐κB and IRF3 activity, RNF114 boosts the production of IFN‐I, suggesting that its genetic dysregulation in psoriasis contributes to pathogenesis by driving excessive inflammatory cytokine production in the skin." (PMID 41362701, 2025).
breast carcinoma (3 papers, 2020 to 2025). "Here, we first described that RNF114 promotes tumor proliferation and autophagy by interacting with EWSR1 and regulating VEGFR2 expression in HER2-positive breast cancer (BC)." (PMID 40092691, 2025).
autoimmune disease (2 papers, 2022 to 2025). A disorder resulting from loss of function or tissue destruction of an organ or multiple organs, arising from humoral or cellular immune responses of the individual to their own tissue constituents. "The role of RNF114 has been elucidated in various studies, underscoring its potential involvement in disease susceptibility, particularly in autoimmune disorders." (PMID 40981192, 2025). "STRING analysis revealed interactions of RNF114 with key immune regulators, and pathway enrichment pointed to roles in NF-κB signaling, ubiquitin-mediated proteolysis, and autoimmune disease pathways." (PMID 40981192, 2025).
cataract (2 papers, 2024 to 2025). Partial or complete opacity of the crystalline lens of one or both eyes that decreases visual acuity and eventually results in blindness. "A deliverable RNF114 complex reduced lens opacity in rats with cold-induced cataracts and zebrafish with oxidative stress-related cataracts." (PMID 41462675, 2025). "A newfound CRYAA E3 ubiquitin ligase, RNF114, plays a central role in aggregate degradation and turnover and proves to have significant reversible effect on different stress-induced cataract models." (PMID 39286982, 2024). "We found that RNF114 did not affect the cell viability of either HLECs or GS iLECs, validating the safety of using RNF114 for the treatment of hypothermic cataracts." (PMID 39286982, 2024). "More importantly, we reveal that fast reversal of hypothermic cataracts in the rat lens can be reproduced by the RNF114 complex, a newly identified CRYAA-related E3 enzyme." (PMID 39286982, 2024). "Leveraging this knowledge gained from hibernators, we engineered a deliverable RNF114 complex and successfully reduced lens opacity in rats with cold-induced cataracts and zebrafish with oxidative stress–related cataracts." (PMID 39286982, 2024). "The newly identified E3 ubiquitin ligase RNF114, related to CRYAA, offers a promising avenue for treating cataracts with protein aggregates." (PMID 39286982, 2024).
pemphigus (2 papers, 2018 to 2022). Pemphigus is a group of rare autoimmune diseases that cause blistering of the skin and mucous membranes (mouth, nose, throat, eyes, and genitals).This conditioncan occur at any age, but often strikes people in middle or older age. "RNF114 is the target gene of miR-338-3p, which probably participates in the regulation of disease activity of pemphigus." (PMID 30083474, 2018). "We suggested that RNF114 was up-regulated through other pathways in pemphigus patients as it could promote T-cell activation." (PMID 30083474, 2018). "However, contrary to the results in vitro, mRNA and protein level of RNF114 was up-regulated in pemphigus patients compared with normal population." (PMID 30083474, 2018). "Interestingly, in the Lin study 54, RNF114 may be a potential target gene of miR-338-3p, and enhancing miR-338-3p could distinctly inhibit RNF114 expression with pemphigus." (PMID 35069903, 2022). "Finally, RNF114 was found as a direct target gene of miR-338-3p, which could promote T-cell activation and probably participates in the immune regulation of pemphigus." (PMID 30083474, 2018).
gastric cancer (1 paper, 2022). A primary or metastatic malignant neoplasm involving the stomach. "We explored the relationship between RNF114 and gastric cancer using bioinformatics and molecular biology techniques." (PMID 35069903, 2022). "Functional assays suggested that RNF114 silencing suppressed the proliferation and metastasis of gastric cancer cells to a certain extent." (PMID 35069903, 2022). "Together, the present results highlight the detrimental effects of RNF114 overexpression in gastric cancer and contribute to a better understanding of the mechanisms underlying RNF114 functionality." (PMID 35069903, 2022). "The results showed that RNF114 was highly expressed in gastric cancer and negatively correlated with the patient's prognosis." (PMID 35069903, 2022).
melanoma (1 paper, 2023). A malignant, usually aggressive tumor composed of atypical, neoplastic melanocytes. "Through LASSO regression, the following six genes were specifically identified to have an irreplaceable prognostic effect on melanoma patients: MLKL, PARVA, PKP1, PSME1, RNF114, and TROAP." (PMID 37127623, 2023). "Finally, six LLPS-related genes (MLKL, PARVA, PKP1, PSME1, RNF114, and TROAP) constitute the prognostic model and predicted clinical outcomes in melanoma patients." (PMID 37127623, 2023).
oral cancers (1 paper, 2022). "Interestingly, to the best of our knowledge, apart from EHF, no studies have reported the association of THOP1, RNF4, GET4 and RNF114 with oral cancers." (PMID 36142544, 2022). "Transcriptome analysis suggested that miRNA-1307-5p could promote oral cancer progression by suppressing THOP1, EHF, RNF4, GET4 and RNF114." (PMID 36142544, 2022).
ovarian carcinoma (1 paper, 2023). A malignant neoplasm originating from the surface ovarian epithelium. "Consistent with the model where nimbolide covalently targets RNF114, these analogs (2 and 3) completely lost their cytotoxic activity [median inhibitory concentration (IC50) > 10 μM] against UWB1 cells (a BRCA1mut ovarian cancer cell line; see more discussion below)." (PMID 37878693, 2023).
cancer (10 papers, 2015 to 2025). A tumor composed of atypical neoplastic, often pleomorphic cells that invade other tissues. "Previous studies have shown that inhibition of RNF114 E3 ligase activity by Nimbolide treatment can result in trapping of PARP1 and synthetic lethality in BRCA-mutated cancers, suggesting its E3 ligase role in tumor progress." (PMID 40092691, 2025). "PARP inhibitors such as olaparib, niraparib, rucaparib, and talazoparib are currently being used to treat various cancers, and the natural product nimbolide has been shown to target RNF114, preventing its ubiquitylation and degradation of PARP1." (PMID 41039157, 2025). "Red fluorescence (RNF114 protein staining) levels were lower in normal tissues than in cancer tissues." (PMID 35069903, 2022). "RNF114, a member of the E3 ubiquitin ligase family, was first identified as a zinc-binding protein that exhibits frequent genomic amplification across various cancers." (PMID 40092691, 2025). "Bioinformatics analysis suggested that miR-1307-5p promotes cancer progression by suppressing key tumor suppressor genes such as THOP1, EHF, RNF4, GET4, and RNF114." (PMID 40699851, 2025). "Bioinformatics analysis revealed that miR-1307-5p likely contributes to cancer progression by downregulating tumor-suppressive genes, such as THOP1, EHF, RNF4, GET4, and RNF114." (PMID 40699851, 2025). "Our results point to the exciting possibility of therapeutically targeting the RNF114-mediated PARP1 trapping pathway by nimbolide and its analogs for the treatment of BRCAmut cancers." (PMID 37878693, 2023). "Nimbolide inhibits RNF114 to induce PARP1 trapping, and its analogs hold promise as therapeutic agents for BRCAmut cancers." (PMID 37878693, 2023).
tumor (8 papers, 2020 to 2025). "Our results showed a 41% reduction in average tumor volume in mice injected with RNF114 knockdown cells compared to those injected with shNC cells (p <0.0001)." (PMID 40092691, 2025). "In a recent study 49,50, nimbolide was shown to recruit and inactivate RNF114 covalent modifications via cysteine-8 (C8) binding in RNF114, thereby protecting tumor suppressors from ubiquitylation." (PMID 35069903, 2022). "However, it's important to reveal novel functions and interacting molecules of RNF114 in tumor progression." (PMID 40092691, 2025). "Knockdown of RNF114 inhibited tumor growth in the nude mice." (PMID 35069903, 2022). "Here, the genes PTBP1, RNF114, XRN2 and ZNRD1 are described as associated with other neoplasms." (PMID 33057419, 2020). "The IHC results revealed that RNF114 expression was higher in tumor tissues than in adjacent normal tissues." (PMID 35069903, 2022). "Meanwhile, pair-differed analysis indicated that RNF114 expression was markedly higher in the tumor than in the normal group." (PMID 35069903, 2022).
infection (6 papers, 2022 to 2026). The state of being infected such as from the introduction of a foreign agent such as serum, vaccine, antigenic substance or organism. "RING finger protein 114 (RNF114) was shown to suppress the infection of PPRSV via the proteasomal degradation of NSP12, which is involved in K27-linked polyubiquitination." (PMID 39728994, 2024). "The E3 ubiquitin ligase ring finger protein 114 (RNF114) in sea perch (Lateolabrax japonicus) acts as an inhibitor of the RLR signaling pathway during infection with red grouper neuron necrosis virus (RGNNV)." (PMID 39202444, 2024). "In addition, we investigated the effect of knockdown of RNF114 on the expression of IKBKE during SVA infection." (PMID 41319264, 2026). "Thus, we selected Si-3 siRNA sequence for lentivirus packaging and subsequent infection of the two cell lines to constructe stable RNF114-knockdowned cells." (PMID 35069903, 2022). "Similarly, we investigated whether RNF114 affects the expression of type I IFN and ISGs induced by poly (I:C) during SVA infection." (PMID 41319264, 2026).
RNF114 also shares sentences with these, for which no sentence is quoted: adenoma (1 paper); Cachexia (1); Ewing sarcoma (1); glioblastoma (1); lung carcinoma (1); neuroblastoma (1); Obesity (1); Parkinson disease (1); sarcoma (1); viral infections (1).